IL6 (interleukin 6)
Diseases named in the same sentence as IL6 in open-access papers (continued):
Sharing a sentence is not in itself a finding about the gene and the disease.
depression (continued). "However, we did find evidence for an attenuation of the effect of smoking on risk of depression when adjusting for IL-6 activity in MVMR." (PMID 36057695, 2022). "rs2069861 in IL6 was associated with both depression and somatization in our cohort." (PMID 35964023, 2022). "The present findings that SVD and depressive symptoms are characteristic of CF may also be supported by biological studies showing that neuroinflammatory markers associated with SVD and depression (e.g., interleukin-6) are also biomarkers for CF." (PMID 35581389, 2022). "A 6-year follow-up longitudinal study of 2,981 MDD patients showed the associations of diagnosis and symptoms of depression with the interleukin-6 (IL-6) level, along with the ability of the IL-6 level to predict current MDD and greater symptom severity at follow-up." (PMID 36213905, 2022). "Finally, IL-6 was not measured in the UK Biobank cohort, so we were unable to assess associations of serum IL-6 concentrations with depression and anxiety." (PMID 34505025, 2021). "Fatigue and depression caused by elevated interleukin-6, combined with severe weight loss (>10%) and NOD, may represent paraneoplastic syndrome and be early manifestations of PC." (PMID 34485159, 2021). "The field now requires experimental studies of IL-6 modulation in humans and animals to further evaluate causality, potential pathogenic mechanisms, and to assess potential usefulness of (add-on) immunotherapies for depression." (PMID 34135474, 2021). "Furthermore, 28% of rats with T12 contusion SCI suffered from depression which was associated with increased serum levels of interleukin (IL)-6 and IL-1α before and IL-6 and tumor necrosis factor (TNF)-α after injury." (PMID 34220440, 2021). "It should be noted that IL-6 has been implicated in LPS-induced depression of neurogenesis in the LPS model, which, however, is a pure inflammatory model and does neither fully replicate the behavioral sequelae of stress and depression nor discriminate between susceptible and resilient subjects." (PMID 34298958, 2021). "IL-6 could also be a shared mechanism for cardiovascular disease, which is often comorbid with depression and is also associated with IL-6." (PMID 34280516, 2021). "While CRP and IL-6 are commonly measured inflammatory markers, they have multiple pro- and anti-inflammatory roles such as those exerted through IL-6 classic and trans-signalling, which complicates inferences about specific immunological mechanisms conferring risk for depression." (PMID 34135474, 2021). "IL-1β-induced production of IL-6 has not only been shown to increase age-associated cognitive decline, but also lead to depression." (PMID 34220440, 2021). "IL-6 may also contribute to cortisol’s induction of TDO, as increased IL-6 in depression are implicated in elevated hypothalamic–pituitary–adrenal activity and cortisol levels, which in turn activates TDO." (PMID 34072767, 2021). "In rodents, depression-like behavior induced by the use of chronic social defeat stress, male sterility, and luteinizing hormone has been associated with higher levels of pro-inflammatory IL-1β, IL-6, and TNF-α." (PMID 34531719, 2021). "The field now requires experimental studies of IL-6 modulation in humans and animals to further examine causality, pathogenic mechanisms, and therapeutic potential of anti-IL-6 and other immunotherapies for depression." (PMID 34505025, 2021). "Indeed, higher levels of IL-6 in childhood, likely because of adverse events, have been associated with increased risk of depression in adulthood and shown to predict stress resilience in animal models of chronic stress." (PMID 34298958, 2021). "Furthermore, metyrapone treatment appeared to actively increase levels of IL-6, with this increase associated with more severe depression after the intervention period." (PMID 33669254, 2021).
depression (continued). "Indeed, some genetic epidemiological studies have shown significant associations between the severity of depression and polymorphisms in inflammatory cytokine genes encoding IL-1β, IL-6, TNF and CRP." (PMID 34351967, 2021). "Evidence for similar, longitudinal, dose-response associations suggest that elevated childhood IL-6 could be a shared risk factor for adult psychosis and depression." (PMID 33684738, 2021). "Mechanistically, the observed increased depression risk conferred by IL6R SNPs that increase CRP levels could happen as a result of either increased IL-6 classic or trans-signalling." (PMID 34505025, 2021). "Although we adjusted for sex, ethnicity, social class and BMI, as with all observational research, residual confounding still might explain the associations of IL-6 with depression and psychosis." (PMID 33684738, 2021). "In addition, we report some evidence for a potential causal role of IL-6 in depression, although this was evident only in MVMR analysis." (PMID 34280516, 2021). "One potential explanation could be that IL-6 classic and trans-signalling have divergent effects on depression risk." (PMID 34505025, 2021). "IL-6 is a cytokine that is significantly associated with depression." (PMID 34976096, 2021). "AR with neuroinflammatory markers may trigger allergies caused by IL-4, IL-5 and IL-6 and, thus, affect psychopathology, such as depression, that may be associated with increased inflammatory markers." (PMID 34689833, 2021). "Therefore, experimental human and animal studies that directly modulate individual IL-6 pathways are required to triangulate the potential causal mechanisms of IL-6 in schizophrenia and in depression." (PMID 34280516, 2021). "In the future, data obtained by following a series of changes in SERT and serum IL-6 could be used as a diagnostic tool for rats or patients who suffer from chronic refractory pain that would tend to develop depression later." (PMID 34680606, 2021). "However, none of the previously conducted meta-analysis studies reported any association of depression or its severity with IL-6, IL-1β, and TNF-α." (PMID 34975391, 2021). "Research additionally demonstrates correlation between elevated inflammatory cytokines and depressive symptoms, and increased levels of the inflammatory markers high-sensitivity C-reactive protein (hs-CRP) and IL-6 have been shown to be risk factors for subsequent depression." (PMID 33967944, 2021). "Replicated findings confirmed that depression is associated with increased IL-6." (PMID 31941442, 2020). "Interleukin-6 (IL-6) levels and depression are positively associated in clinical studies." (PMID 31941442, 2020). "Raised pre-treatment plasma levels of IL-6 was associated with treatment resistance to depression." (PMID 31941442, 2020). "Interestingly, the increase in IL-6 in childhood enhances the risk of developing depression later in life, and there is a relationship between high IL-6 levels and depression in patients with PD." (PMID 32046139, 2020). "The dysregulation of the α2-AR pathway may contribute to the release of pro-inflammatory cytokines, such as tumor necrosis factor-α (TNF-α), interleukin-1 (IL-1) and IL-6, thus increasing the susceptibility to depression." (PMID 33551951, 2020). "In addition to these severe metabolic problems, IL-6 can cross the blood–brain barrier, where it is recognised by groups of hypothalamic and hippocampal neurons controlling food intake and causing depression." (PMID 33114676, 2020). "Studies had tested the association of IL-6 levels in physical disorders associated with depression." (PMID 32235786, 2020). "IL-6 is a multifunctional pro-inflammatory cytokine that is produced in response to inflammatory stimuli and secreted by macrophages and monocytes, playing a key role in important biological pathways underlying stress and stress-induced depression." (PMID 32655450, 2020).
depression (continued). "Increased IL-6 activity may cause depression through activation of hypothalamic-pituitary-adrenal axis or influence of the neurotransmitter metabolism." (PMID 32235786, 2020). "Study has tested the association between IL-6 levels and depression severity." (PMID 32235786, 2020). "According to Maes and coworkers, increased interleukin production, such as Il-1β and Il-6, by monocytes in severe depression might underlie the various aspects of the immune and “acute” phase responses detectable in major depressive disorders." (PMID 32046139, 2020). "Increased IL-6 is considered to be correlated with cortisol and could be a risk factor for psychological problems, such as depression and anxiety." (PMID 33255406, 2020). "Nevertheless, RA therapeutics inhibiting pathogenetic pro-inflammatory cytokines like tumor necrosis factor (TNF) and interleukin-6 (IL-6) alleviate symptoms such as depression and anxiety and were linked to a reduced risk of future neurodegeneration in RA patients." (PMID 33362800, 2020). "We speculate that cytokines manufactured in macrophages following the miR-146a-5p treatment are likely the cause of CM depression as cytokines such as both IL-6 and TNF-α are known cardiac depressants." (PMID 32958516, 2020). "Further investigation is needed to understand this discrepancy, which could be linked to divergent effects of IL-6 classical and trans signalling on depression risk, and/or CRP-dependent vs CRP-independent effects of IL-6 on depression risk." (PMID 30886334, 2020). "Finally, we explored the mechanism of susceptibility of CUMS-induced depressive disorder to glucose metabolic disorder in hypothalamus based on IL-6-mediated glucose homeostasis signaling." (PMID 32655424, 2020). "In particular, IL-6 has been linked to CSDS-related depression and anxiety." (PMID 31057357, 2019). "Similarly, higher baseline CRP and IL-6 levels are not only associated with cognitive symptoms of depression but also predict cognitive symptoms at an average follow-up of 11.8 years, suggesting that inflammation precedes the progression of MDD." (PMID 30995920, 2019). "The mechanisms by which IL-6 signaling may contribute to stress susceptibility and depression are unknown." (PMID 31057357, 2019). "In addition, one study has noted that the development of depression and psychosis in young adulthood was associated with higher levels of IL-6 in childhood." (PMID 30937313, 2019). "Notably, the clinical study showed that the advanced cancer patients with elevated levels of plasma IL-6 simultaneously developed malnutrition and were associated with anemia, anorexia, and depression." (PMID 31010015, 2019). "Cytokine profiles for different animal models of depression indicates that various forms of stress exposure induces the release of pro-inflammatory cytokines such as INF-γ, IL-1β, and IL-6, which implicates immune responses as an underlying mechanism of depression caused by stress." (PMID 31312123, 2019). "Serum and CSF levels of IL-6 have previously been linked to depression and mortality in PD,45–47 and our results further suggest that underlying inflammatory phenotypes may contribute to a greater risk of progression to depression in PD patients." (PMID 31372494, 2019). "Moreover, the authors used weighted gene co-methylation network analysis (WGCNA) to identify networks of co-methylated modules that are associated with depression, TL, and IL-6 levels." (PMID 30650526, 2019). "IL-6 plays a key role in the development of stress-associated depression-like behaviors in mice." (PMID 31849598, 2019). "Major depressive disorder is also associated with increased plasma levels of proinflammatory cytokines, such as interleukin (IL)-6 and tumor necrosis factor (TNF)-α, that may play a role in the disease’s pathogenesis." (PMID 31847190, 2019).
depression (continued). "Furthermore, elevation of TNF-α and IL-6 levels was associated with a lower VT score, as well as a lower score for MH (which is used for detection of depression) in subjects with pulmonary hypertension." (PMID 31394768, 2019). "Furthermore, animal models of inflammation-associated depression are often generated through the administration of cytokines or cytokine inducers, including IL-6 and lipopolysaccharide (LPS)." (PMID 31881712, 2019). "Diets with higher n-6: n-3 PUFA ratios, for example, may enhance risk of both depression and inflammatory diseases, characterized by higher levels of IL-6 and TNF-α." (PMID 30445703, 2018). "In particular, TNFα and IL-6 have been associated with antidepressant-resistant depression." (PMID 30423923, 2018). "Therefore, IL-6 is implicated in acutely-derived or chronically-derived stressors of depression, and it is an important target for anti-inflammatory agonists that support M2-macrophage expansion." (PMID 29941796, 2018). "In an animal model of depression, sustained increases in central nervous system IL-6 may play a pathophysiological role underlying treatment resistance to antidepressants." (PMID 29103192, 2018). "Depression is associated with obesity and visceral fat is the major site for IL-6 secretion, which may explain the relationship between depression, inflammation, metabolic risk factors and cardiovascular diseases." (PMID 30248896, 2018). "Furthermore, raised levels of the inflammatory cytokine IL-6 in childhood are associated with an increased risk of developing depression and psychosis in young adulthood, and persistent depressive symptoms during the second decade of life." (PMID 29544672, 2018). "Although evidence for associations between IL-6, depression and psychosis remained after controlling for a number of potential confounders, residual confounding from unmeasured factors still might account for these associations." (PMID 29197507, 2018). "Genetic variation in IL-6 is associated with this expression of depression." (PMID 28278190, 2017). "This study provides evidence that both depression and antidepressant use may be associated with altered IL6 DNA methylation in buccal epithelia cells." (PMID 29070016, 2017). "As a marker of inflammation measured in the periphery, high CRP may reflect activity of more upstream pro-inflammatory factors, such as IL-6 and IL-1B which may themselves induce changes in brain function predisposing to depression." (PMID 28809860, 2017). "Interestingly, higher levels of CRP and IL-6 during childhood (age of nine years) were shown to be a predictor of higher risk of depression and psychosis in later life." (PMID 29181395, 2017). "This is in line with our association regarding decreased IL6 methylation in depression." (PMID 29070016, 2017). "Drawing on data and biospecimens gathered from a prospective study of psychiatric disorders, we investigated whether IL6 methylation in a peripheral tissue is associated with depression status." (PMID 29070016, 2017). "Indeed, IL-6 has been proposed as a molecular bridge between circadian and inflammatory processes in a chronobiological animal model of depression and is implicated in circadian rhythmicity and in the circadian regulation of sleep drive." (PMID 28382017, 2017). "Further examples include the hypoxia inducible factor 3 alpha subunit (Hif3a), whose expression was found to be increased in schizophrenic and bipolar patients or Sgk1 and Tsc22d3, which were associated with high interleukin (IL)-6 levels in patients suffering from the major depressive disorder." (PMID 27188165, 2016). "Inflammation has been demonstrated to be associated with depression and exposure to stressors, specifically including the action of the inflammatory cytokines interleukin-6 (IL-6) and tumour necrosis factor (TNF6, 7, 8, 9) and the acute-phase protein C-reactive protein (CRP10, 11, 12)." (PMID 27898068, 2016).
depression (continued). "While previous studies with MI and other clinical populations suggest that cardiac function, comorbidities, sleep, depression, anemia, interleukin 6 (IL-6), and social support are independently associated with fatigue, no studies have systematically examined these factors and fatigue post-MI." (PMID 27148509, 2016). "In contrast to the previous observations on the depressive symptoms at 5-year follow-up (incident depression), acute inflammation largely explained the association between IL-6 and persistent depressive symptoms in the fully adjusted model 3 (OR = 2.02, p = 0.107)." (PMID 25877654, 2016). "Indeed, it has been already observed that both COPD and depression are associated with increased levels of IL-6." (PMID 26403459, 2016). "Increased levels of proinflammatory cytokines, such as TNF-α and IL-6, have been associated with cases of depression and as per a recent study, inhibition of TNF-α prevents cognitive decline and maintains hippocampal brain-derived neurotrophic factor (BDNF) levels." (PMID 26835453, 2016). "Whether the raised IL10 production is a response to the inflammation associated with depression in our cohort, we found raised IL6 and TNFα only in the hip fracture patients who developed depressive symptoms, remains to be shown but is one possibility." (PMID 26112234, 2016). "In this study, we observed that both COPD and depression are associated with increased inflammation as demonstrated by increased levels of IL-6 in patients diagnosed either with COPD or with rDD and with chronic obstructive pulmonary disease with comorbid depressive symptoms (COPD + DS)." (PMID 26403459, 2016). "After adjustment for age, education level, number of years of completed education, illness duration, total PANSS score, depression severity and chlorpromazine equivalent, there was still a positive association between IL-6 and hsCRP levels and worse cognitive performance." (PMID 25214388, 2015). "In patients with depression and anxiety inflammatory reaction and mild chronic inflammation were observed to be caused by increased concentration of proinflammatory cytokines like TNFα, IL-1α, IL-1β, IL-4, IL-5, IL-6, IL-12, IFNγ, and C-reactive protein." (PMID 26078821, 2015). "Furthermore, it has been described that IL-6 has important effect on the CNS and has been implicated in different diseases such as MS, Parkinson, and depression." (PMID 25838828, 2015). "Remarkably, the direct secretion of cytokines in tumor cells is also involved in cancer-related depressive symptoms as development of depression may be linked to elevated plasma IL-6 and ascites in patient with ovarian cancer." (PMID 25309465, 2014). "Major depression (MD) has been reported to be associated with OS and with inflammation endpoints, namely, excess levels of IL-6, IL-10, and IL-6/IL-10 ratio versus F2-isoprostanes, along with increased protein carbonylation and expression of GR, GPx, SOD, and CAT." (PMID 24876913, 2014). "Moreover, IL-6 has been suggested to be associated with brain-derived neurotrophic factor (BDNF) which is highly involved in the physiopathology of depression." (PMID 24795767, 2014). "However, IL-6 has also been linked to different diseases, such as diabetes, atherosclerosis, depression, Alzheimer's disease and rheumatoid arthritis." (PMID 23985898, 2013). "Moreover, depression was associated with high IL-6 serum levels and increased cardiovascular mortality risk." (PMID 23847549, 2013). "Protein elevations of both cytokines in serum and CSF are a consistent finding in depression, with some studies suggesting that IL-6 is specifically associated with medication-refractory depression, and that IL-10 levels decrease following successful treatments." (PMID 24143878, 2013). "One of several possible hypotheses is that the number of somatic symptoms in depression reflects increasing levels of IL-6 in the brain, which correlates with suicidal behavior caused by low levels of intracerebral serotonin." (PMID 22839681, 2012).